RAD51C (RAD51 paralog C)
Diseases named in the same sentence as RAD51C in open-access papers (continued):
Sharing a sentence is not in itself a finding about the gene and the disease.
ovarian carcinoma (continued). "The current panel of genes with strong evidence for use in clinical practice include PALB2, CHEK2, ATM, RAD51C and RAD51D with additional genes such as BARD1 (breast cancer) and BRIP1 (ovarian cancer) continuing to emerge." (PMID 39107016, 2024). "In that study, among 20 heavily pretreated, mostly platinum-resistant, ovarian cancer patients with prior PARP inhibitors (PARPi), four with germinal LoF alterations in BRCA1 and RAD51C genes attained PRs32." (PMID 38555285, 2024). "In the course of our study, the ovarian cancer gene panel consisted of the five core genes (BRCA1, BRCA2, BRIP1, RAD51C and RAD51D), and it is likely that the gene panel will be expanded with other cancer genes, such as PALB2, in the near future." (PMID 34617209, 2022). "The prevalence of a personal or family history of ovarian cancer among women with PVs in BRIP1, RAD51C, or RAD51D was similar to that observed for women with PVs in BRCA1 or BRCA2 in this cohort." (PMID 33926482, 2021). "PVs in RAD51C and RAD51D were identified in 0.5% (149/27,915) and 0.3% (74/27,915) of women with ovarian cancer, respectively." (PMID 33926482, 2021). "Overall, testing for moderate- or high-penetrance BRCA1/2, RAD51C, RAD51D, BRIP1, and mismatch repair genes for the patients with epithelial ovarian cancer is recommended." (PMID 34207568, 2021). "PVs in BRIP1, RAD51C, or RAD51D were identified in 0.5% of all tested women but in 1.6% of women with a history of ovarian cancer (~ 3-fold increase)." (PMID 33926482, 2021). "Similar to BRCA2, the median age of ovarian cancer diagnosis was older for women with a PV in BRIP1 (65 years), RAD51C (62 years), or RAD51D (57 years)." (PMID 33926482, 2021). "The median age at ovarian cancer diagnosis of women with a PV in BRIP1, RAD51C, or RAD51D was much older and more than three quarters of women with a PV in one of these three genes and a history of ovarian cancer was diagnosed after the age of 50." (PMID 33926482, 2021). "Previous studies on breast and ovarian carcinoma (BC and OC) revealed constitutional BRCA1 and RAD51C promoter hypermethylation as epigenetic alterations leading to tumor predisposition." (PMID 32276467, 2020). "Some of these downstream FA genes are known as tumor suppressor genes in other monoallelic inherited cancers like breast and ovarian cancer (FANCD1 = BRCA2, FANCS = BRCA1, FANCN = PABLB2, FANCJ = BRIP1, FANCO = RAD51C)." (PMID 32397406, 2020). "A number of the RAD51 mediators have now been added to the more comprehensive breast and ovarian cancer screening panels (i.e., PALB2, RAD51C, RAD51D, XRCC2)." (PMID 30551670, 2018). "In this study, we analysed the five RAD51 paralogs (RAD51B, RAD51C, RAD51D, XRCC2, XRCC3) in 142 unrelated patients with breast and/or ovarian cancer to estimate their contribution to breast and ovarian cancer predisposition." (PMID 24139550, 2013). "Mutations in BRCA1, BRCA2, RAD51C, and PALB2 genes were already shown to correlate with the risk of ovarian cancer, but not with BOTs." (PMID 35313928, 2022). "The age at ovarian cancer diagnosis was older for women with PVs in BRIP1, RAD51C, or RAD51D, suggesting that it is safe to delay RRSO until age 45–50 in RAD51D PV carriers and possibly until age 50–55 in BRIP and RAD51C PV carriers." (PMID 33926482, 2021). "This suggests that panel testing may help guide treatment selection for women with ovarian cancer by identifying PVs in BRIP1, RAD51C, or RAD51D." (PMID 33926482, 2021). "This association was confirmed in breast and/or ovarian cancer families and cohorts with no known BRCA1 or BRCA2 mutations, leading to the proposition to include RAD51D and RAD51C to the list of genes screened for breast cancer predisposition." (PMID 34208195, 2021). "The ovarian cancer risk was associated with mutations in BRCA1, BRCA2, RAD51C, and PALB2 but not in the CHEK2 gene." (PMID 33670479, 2021).
ovarian carcinoma (continued). "Notably, in patients with ovarian cancer, a significant number of PVs were identified in the moderate penetrance RAD51 genes; RAD51C (1.5%) and RAD51D (1%), followed by the MMR and ATM genes." (PMID 34326862, 2021). "Therefore, RAD51C and RAD51D genes are included in several hereditary breast/ovarian cancer screening panels." (PMID 33015624, 2020). "Loss-of-function variants in RAD51C and RAD51D increase the risk of breast and ovarian cancer, but the same has not been demonstrated for other RAD51 paralogs, or for RAD51 itself that plays a major role in HR repair." (PMID 33333735, 2020). "Deletion of RAD51C and RAD51D alleles has been reported to moderately increase the lifetime ovarian cancer risk by 5–15%, but not RAD51B." (PMID 31366178, 2019). "Mutations in RAD51C and RAD51D are rare and have been primarily linked to an increased risk for ovarian cancer rather than breast cancer alone." (PMID 28874143, 2017). "The associations are even stronger when only specific-cancer genes are considered: all specific-cancer genes in the DSBR class are associated with estrogen-related tissues (CHEK2, breast cancer; RAD51C and RAD51D, ovary cancer; and the DSBR cancer gene BRCA1, breast and ovary)." (PMID 26856619, 2016). "Previous analysis of RAD51C pathological mutants showed a more prominent role of RAD51C in DSB repair which might contribute to the suppression of FA and subset of breast and ovarian cancer." (PMID 26354865, 2015). "In addition, the last V5 version of BOADICEA incorporates the effects of pathogenic variants (PVs), not only in BRCA1 and BRCA2 genes, but also in PALB2, CHEK2, ATM and BARD1 for the breast cancer model and RAD51D, RAD51C and BRIP1 for the ovarian cancer model." (PMID 35886069, 2022). "RAD51C (MIM#602774) loss-of-function variants are significantly associated with BC risk (OR = 1.93), while this association is even greater with estrogen-receptor-negative BC, triple-negative BC, and ovarian cancer (OR = 3.99, 5.71, and 5.59, respectively)." (PMID 35740625, 2022). "Also mutations in RAD51C have not been found to increase the risk of breast cancer and mutations in RAD51D have been associated with high risk of ovarian cancer but not with breast cancer." (PMID 29566657, 2018). "Similarly, in relapsed platinum-sensitive high-grade ovarian cancer patients, therapeutic responses to Rucaparib were not restricted to BRCA-mutated tumors, and were observed in several patients with mutations to other HR genes including ATM, NBN, RAD51C, and RAD51D." (PMID 35205643, 2022).
breast cancer (197 papers, 2010 to 2026). A primary or metastatic malignant neoplasm involving the breast. "One NOA patient with bilateral cryptorchidism and severe hypospadias carried two previously reported truncating variants in FA genes, BRIP1 p.Thr912fs and RAD51C c.1026 + 5_1026 + 7del." (PMID 40060932, 2025). "Here, we present a rare case of primary breast cancer following primary fallopian tube cancer in a RAD51C mutation carrier, treated with niraparib." (PMID 38360632, 2024). "Four Fanconi anemia (FA) genes (BRCA1, BRCA2, PALB2 and RAD51C) are defined as breast cancer (BC) susceptibility genes." (PMID 37566130, 2023). "Genome-wide investigation of rare coding region CNVs in 98 high-risk Northern Finnish breast cancer cases revealed recurrent alterations in RAD51C, RAD52 and HSD17B14 genes." (PMID 37578974, 2023). "In the current study the RAD51C duplication CNV allele had two-fold frequency in the breast cancer cases compared to controls." (PMID 37578974, 2023). "Secondly, heterozygous hypomorphic germline mutations in BRCA2 + RAD51C are also found in families with a history of breast cancer susceptibility." (PMID 36906610, 2023). "We analyzed the overall survival of patients with tumors harboring BRCA2, RAD51C or combinations of BRCA2 + RAD51C mutations using the breast cancer genome datasets available at cBioportal.org39,40." (PMID 36906610, 2023). "Nevertheless, truncating variants in BARD1, BRIP1, and RAD51C are associated with a moderate risk of female BC, generally accounting for less than 1% of Breast Cancers." (PMID 35053526, 2022). "XRCC3 forms a functional complex (the CX3 complex) with another RAD51 paralog, RAD51C, whose LoF events are also mainly caused by gene silencing, in this case in breast cancer samples." (PMID 36969741, 2022). "Given the breast cancer risk, future studies on RAD51C and EC risk will need to account for tamoxifen exposure, same as for BRCA1/2 genes." (PMID 33917078, 2021). "In the framework of the BRIDGES project (Breast Cancer Risk after Diagnostic Gene Sequencing), the RAD51C gene has been sequenced in 60,466 breast cancer patients and 53,461 controls." (PMID 33333735, 2020). "We have shown that aberrant splicing of RAD51C represents a relevant pathogenic mechanism in breast cancer susceptibility." (PMID 33333735, 2020). "The purpose of this study was to estimate precise age-specific tubo-ovarian carcinoma (TOC) and breast cancer (BC) risks for carriers of pathogenic variants in RAD51C and RAD51D." (PMID 32107557, 2020). "Several FA genes, such as BRCA1/FANCS, BRCA2/FANCD1, PALB2/FANCN, and RAD51C/FANCO have been confirmed to be breast carcinoma susceptibility genes at present." (PMID 32300589, 2020). "For example, mutational signature analysis in breast cancers revealed that promoter methylation of RAD51C had a similar effect on HR deficiency as biallelic inactivation of BRCA1/2." (PMID 30497521, 2018). "So far, while BRCA2, BRIP1, PALB2, and RAD51C are associated with high or moderate breast cancer risk, the impact of SLX4 on breast cancer remains to be measured." (PMID 22383991, 2012). "Some of the genes causing the Fanconi anemia (FA) syndrome, such as BRCA2, BRIP1, PALB2, and RAD51C, are associated with high or moderate risk of developing breast cancer." (PMID 22383991, 2012).
breast cancer (continued). "These include Rad52, the human Rad51 paralogs Rad51B, Rad51C, Rad51D, Xrcc2, and Xrcc3, and breast cancer susceptibility gene Brca2." (PMID 21129202, 2010). "RAD51C (FANCO) is classified as a moderately penetrant breast cancer susceptibility gene." (PMID 41528496, 2026). "Furthermore, RAD51C is a Fanconi Anemia suppressor gene, a rare recessive genetic disorder resulting in hematological and developmental defects and cancer, with the same RAD51C mutation found in both Fanconi Anemia and breast cancer patients." (PMID 37488098, 2023). "In addition, the methylation of homologous recombination gene promoters such as BRCA1 and RAD51C lead to homologous recombination-deficient breast cancer development in sporadic cases." (PMID 37504297, 2023). "The National Comprehensive Cancer Network (NCCN) guidelines report on mutations in BRIP1 and RAD51C as being a cause for potential increase in breast cancer risk (specifically for triple negative breast cancers), but there is insufficient evidence for risk management." (PMID 35053526, 2022). "All patients carrying a pathogenic CHEK2 or RAD51C variant had breast cancer." (PMID 34680878, 2021). "Furthermore, BRCA1 promoter hypermethylation has been shown to be a common early event in the development of TNBC, and epigenetic silencing of RAD51C, which is also strongly associated with signature 3 in basal-like breast cancer." (PMID 33227964, 2020). "However, the magnitude of breast cancer risk, if any, associated with monoallelic germline RAD51C mutations is uncertain." (PMID 26484312, 2015). "RAD51C mutation leads to FA-like disorder, and are associated with inherited breast cancer." (PMID 26354865, 2015). "Moreover, the newly ascertained FA gene RAD51C harbored a truncating mutation in 4/1,100 (0.5%) of familial breast cancer cases from Germany." (PMID 22383991, 2012). "Interestingly, RAD51C is located in chromosomal region 17q23, which is amplified in primary breast cancer tumors, but it hadn't been investigated previously as a susceptibility locus for breast cancer." (PMID 21980511, 2011). "Most breast cancer susceptibility genes are involved in the damage repair signaling pathway, i.e., including BRCA1, BRCA2, PALB2, CHEK2, ATM, BARD1, RAD51C, and RAD51D." (PMID 40649769, 2025). "For example, except for retinoblastoma, MutL Homolog 1 (MLH1) is frequently silenced in colorectal and endometrial cancers, while methylation of BRCA1 and RAD51C is commonly detected in ovarian and breast cancers." (PMID 41150792, 2025). "For instance, beyond the well-known BRCA mutations in breast cancer, alterations in genes such as BARD1, and pathogenic variants of RAD51C and RAD51D, reported to be associated with increased breast cancer risk, have also been identified." (PMID 40723883, 2025). "RAD51C/RAD51D-mutated cancers and BRCA2/RAD51C hypermethylation in male breast cancer (~30% prevalence) expand PARPi candidacy]." (PMID 40864792, 2025). "Eight different genes, including ATM, BRCA1, BRCA2, CHEK2, PALB2 (FANCN), RAD51C, and RAD51D, demonstrate significant correlations with an increased risk of breast cancer when harboring pathogenic variations." (PMID 40800071, 2025). "While BRCA1/2 mutations are the standard in clinical testing, other HRR pathway genes, such as PALB2 and RAD51C, have potential applications in determining breast cancer treatment." (PMID 38397152, 2024). "Variants involving ATM, CHEK2, BRIP1, RAD51C, RAD51D, NBN and BARD1 are known to be associated with a moderately increased risk of breast cancer and a lifetime risk of around 25%." (PMID 38439815, 2024). "This economic evaluation estimates the cost-effectiveness of prevention strategies for ovarian and breast cancer among individuals with pathogenic variants in cancer susceptibility genes BRCA1, BRCA2, PALB2, RAD51C, RAD51D, and BRIP1." (PMID 38334999, 2024).
breast cancer (continued). "While BRCA1 and BRCA2 remain the most well-known high-penetrance genes, others, such as ATM, BARD1, CHEK2, PALB2, RAD51C, and RAD51D, are now recognized as conferring moderate to high risk for breast cancer." (PMID 39590369, 2024). "Of 113 patients carrying RAD51C, 32 (28.3%) had received a diagnosis of breast cancer, and 4 women had a second primary breast cancer." (PMID 38648056, 2024). "Many studies have confirmed that RAD51C and RAD51D germline pathogenic variants are closely associated with the development of ovarian and breast cancer." (PMID 39206620, 2024). "Other homologous recombination DNA damage repair (HR-DDR) genes associated with breast cancer risk accounted for 15.9% (13/82) of the carriers, including ATM (n = 2), BARD1 (n = 4), CHEK2 (n = 1), PALB2 (n = 2), RAD51C (n = 1), and RAD51D (n = 3)." (PMID 38893140, 2024). "Specifically, PVs in PALB2, ATM, CHEK2, RAD51C, and RAD51D are associated with increased lifetime breast cancer risk, ranging from 20% to 58%, depending on the defective gene and identified variant, while influenced by family history." (PMID 39001430, 2024). "The loss-of-function (LOF) classification of most missense variants in tumor suppressor breast cancer genes BRCA1, BRCA2, PALB2, and RAD51C remains unclassified and confounds clinical actionability." (PMID 39430403, 2024). "Recent comprehensive studies have highlighted that pathogenic variants (PVs) across eight distinct genes, such as ATM, BRCA1, BRCA2, CHEK2, PALB2 (FANCN), RAD51C, and RAD51D, exhibit a substantial correlation with breast cancer risk." (PMID 38397209, 2024). "According to the NCCN guidelines v2.2024 (27 September 2023), germline PVs in the genes ATM, BARD1, RAD51C, RAD51D, NF1, and CHEK2 confer an absolute breast cancer risk between 17% and 40%." (PMID 38893140, 2024). "RAD51C expression is significantly increased in breast cancer and studies have also shown that clinicopathological features of early or familial gastric cancer are significantly correlated with the expression of RAD51C16." (PMID 38297111, 2024). "Tumor suppressor genes BRCA1, BRCA2, PALB2, and RAD51C play crucial roles in homology-directed recombination DNA repair (HDR) activity, and mutations in these genes have been implicated in breast cancer." (PMID 39430403, 2024). "The estimated cumulative risks of developing tubo-ovarian carcinoma (TOC) and breast cancer (BC) at 80 years of age were 11% (95% CI:6–21%) and 21% (95% CI:15–29%) for RAD51C, respectively." (PMID 38360632, 2024). "How cost-effective are ovarian and breast cancer risk reduction strategies among women with pathogenic variants in individual cancer susceptibility genes (ie, BRCA1, BRCA2, PALB2, RAD51C, RAD51D, and BRIP1)?" (PMID 38334999, 2024). "Frequency of RAD52, HSD17B14 and RAD51C CNV carriers in the studied breast cancer cases and controls." (PMID 37578974, 2023). "Carriers of PALB2, BARD1, RAD51C, RAD51D, ATM, and CHEK2 are at higher risk of breast cancer as well." (PMID 37458761, 2023). "Variants in key genes of HR, such as BRCA1, BRCA2, PALB2, BARD1, RAD51C, and RAD51D, which alter their function and/or their expression, have a significant association with breast cancer risk." (PMID 37372450, 2023). "The BC susceptibility genes involved in breast cancer which cause moderate risk are BRIP1, CHEK2, ATM, RAD51C, and PALB2." (PMID 36873936, 2023).